INS (insulin)
Diseases named in the same sentence as INS in open-access papers (continued):
Sharing a sentence is not in itself a finding about the gene and the disease.
Insulin resistance (continued). "Intrahepatic triglycerides (IHTG) may be an important variable in hepatic insulin resistance (1, –, 4), and excess triglycerides may be associated with generation of lipid-derived signaling molecules that inhibit insulin action." (PMID 25250633, 2015). "Visfatin may improve insulin sensitivity during the second and third trimesters and up-regulation in insulin resistance associated pregnancy complications may be part of a physiological feedback mechanism to improve insulin signalling." (PMID 26110385, 2015). "Moreover, doxorubicin can decrease expression of genes (IRS1, Glut4, AMPK, and GSK3b) involved in insulin signaling in muscle tissues and thus can cause systemic insulin resistance, thus leading to the development of type 2 diabetes-like condition." (PMID 26089893, 2015). "Indeed, it has been documented that decreased levels of adiponectin are associated with increased insulin levels that accompany insulin resistance." (PMID 26560078, 2015). "Autoimmune destruction of insulin-producing cells underlies the pathophysiology of type 1 diabetes (T1D), whereas chronic metabolic stress linked to obesity and insulin resistance results in a gradual impairment of pancreatic function, demise of β-cells, and ultimately causes type 2 diabetes (T2D)." (PMID 26013143, 2015). "Opinion is also divided as to whether glucose or insulin concentrations, or insulin resistance, are at the root of these associations." (PMID 25940643, 2015). "The treatment efficacy is inversely associated with insulin resistance and other features of metabolic syndrome and may be explained by the inhibitory effect of higher insulin levels on the (treatment-induced) lipolysis." (PMID 26069728, 2015). "Furthermore, the results are in line with the previous studies showing significant associations between the INSRPmlI polymorphism and serum levels of insulin and insulin resistance." (PMID 27141540, 2015). "Also, several hormones associated with insulin resistance and obesity, such as insulin, catecholamines, TNF, and other proinflammatory cytokines, downregulate the expression of adiponectin in adipocytes, resulting in decreased adiponectin serum levels." (PMID 25918733, 2015). "Reduced HRV was associated with insulin resistance and lower insulin sensitivity." (PMID 26277879, 2015). "Furthermore, large adipocytes, which contain more TG in large LD, are associated with insulin resistance while small adipocytes are more responsive to insulin." (PMID 26536476, 2015). "In the present study dMG also led to a pre-diabetic phenotype, which was indicated by the development of insulin resistance in dMG+ mice and we cannot exclude insulin as a potential cause for the observed degenerative changes in vertebral structures of dMG+ mice." (PMID 25668621, 2015). "Also, the INSR PmlI "pp" genotype appeared to confer a decreased risk for serum insulin levels and insulin resistance in the controls." (PMID 27141540, 2015). "Therefore, insulin resistance in the liver is characterized by deficient responses to insulin, such as enhanced gluconeogenesis, which ultimately cause or worsen hyperglycemia." (PMID 26084330, 2015). "Insulin-resistance in type 2 diabetes, obesity, and aging is associated with a marked reduction in the intracellular pool of Glut4 protein in adipose cells, which in turn impairs insulin stimulation of glucose transport." (PMID 26086818, 2015). "However, in contrast to healthy subjects, in our present study, the diabetic patients in the higher UUAE quartiles were associated with reduced insulin sensitivity and increased insulin resistance, which theoretically should result in decreased UUAE." (PMID 25889178, 2015). "In addition both the P- and HV-M1/M2 ratio positively correlated with the insulin levels, therefore M1 polarization was associated also to insulin resistance." (PMID 26599575, 2015).
Insulin resistance (continued). "Indeed, BAT is now known to exert anti-type 2 diabetic effects associated with improvments of dyslipidemia and insulin secretion as well as decrease insulin resistance in type 2 diabetes." (PMID 25688211, 2015). "Therefore, if α-glucosidase inhibitors are effective to regulate blood glucose levels and insulin resistance, then much of the risk reduction can be explained by the combined effects of decreased blood glucose levels and increased insulin sensitivity." (PMID 25774201, 2015). "Despite its insulin sensitizing effects, pioglitazone may induce weight gain leading to an increased risk of development of insulin resistance." (PMID 25615826, 2015). "The major pathophysiological issue for DM patients is insufficient insulin (INS) secretion associated with the destruction of pancreatic islet β-cells and insulin resistance (IR), ultimately resulting in complications in numerous systems, such as the cardiovascular and renal systems." (PMID 26347892, 2015). "Likewise, in the white matter, decreased MTR peak height was significantly associated with OGTT derived measures of insulin resistance, namely, fasted insulin (p = 0.012), AUCinsulin (p = 0.002), HOMA-IR (p = 0.010), and insulinogenic-index (p = 0.032)." (PMID 26074813, 2015). "Given that defective insulin internalization and, consequently, hyperinsulinaemia may also cause secondary insulin resistance in animal models, PKCζ activation could be important for improving insulin sensitivity." (PMID 26398746, 2015). "Increased hepatocyte CYP2E1 expression may also result in the downregulation of insulin signalling, potentially contributing to the insulin resistance associated with NAFLD." (PMID 25873773, 2015). "High-fat diet (HFD)-induced obesity is associated with insulin resistance, which may affect brain synaptic plasticity through impairment of insulin-sensitive processes underlying neuronal survival, learning, and memory." (PMID 26023930, 2015). "Since muscle constitutes the largest portion of insulin-sensitive tissue in the body, decrease in fat-free mass may be an important factor with regard to insulin resistance and risk of T2D." (PMID 26406981, 2015). "Antiresistin oligo treatment significantly decreased fasting serum glucose (Res-oligo versus C-oligo group, P < 0.05) associated with improved insulin resistance, evidenced by a reduction of fasting serum insulin levels (P < 0.01) and reduced HOMA-IR values (P < 0.05)." (PMID 25922835, 2015). "Because coffee is a rich source of anti-oxidants, and sub-clinical inflammation has been implicated in the development of insulin resistance, it was proposed that coffee may improve insulin sensitivity by decreasing inflammation." (PMID 25978631, 2015). "In addition, a recent genome-wide analysis of peripheral blood revealed type-2 diabetes related DNA methylation variations, and another investigated associations between methylation and fasting glucose, insulin and insulin resistance." (PMID 25651499, 2015). "To know whether these changes in DM2 mice are associated with serum insulin content or insulin resistance, we measured the serum insulin level and insulin resistance value (HOMA-IR)." (PMID 26161865, 2015). "This may in turn result into an increased FFA delivery to the liver, consequently stimulates hepatic glucose production by fatty acids (FA) causing interference in hepatic insulin removal, and may further accentuate insulin resistance." (PMID 28702225, 2015). "Taken together, these data indicate that, beside peripheral insulin resistance, reduced brain insulin action may also contribute to loss of maintenance of metabolic control." (PMID 25705204, 2015). "We investigated the effects of inorganic arsenic at doses relevant to human exposure from drinking water on blood glucose and insulin, glucose tolerance, and insulin resistance on estrogen-deficient female mice in the presence or absence of estrogen supplementation." (PMID 25859628, 2015).
Insulin resistance (continued). "The reduction of mtDNAn in obese human subjects is associated with insulin resistance and may arise from increased D-loop methylation, suggesting an insulin signaling-epigenetic-genetic axis in mitochondrial regulation." (PMID 26110043, 2015). "One of the key pathophysiological factors underlying the formation of insulin resistance may be the dysregulation of energy metabolism in insulin-sensitive tissues such as skeletal muscle, liver, and adipose." (PMID 25741283, 2015). "Insulin deficiency or insulin resistance could be responsible for dyslipidaemia because insulin increases fatty acid as well as triglyceride synthesis in adipose tissue and liver." (PMID 24523819, 2014). "We also sought associations between VAT, blood lipids, glucose, insulin and insulin resistance." (PMID 24504765, 2014). "Excess visceral fat accumulation may be causally related to features of insulin resistance as well as to high plasma levels of insulin and glucose." (PMID 24502834, 2014). "As increased seminal insulin is associated with insulin resistance and abdominal obesity, increased insulin exposure during spermatogenesis may potentially develop insulin resistance in the Sertoli cells." (PMID 24885899, 2014). "Additionally, we demonstrated in retinal endothelial cells that TNFα activation of SOCS3 and IRS-1Ser307 leads to decreased insulin signal transduction, which likely underlies insulin resistance." (PMID 24695399, 2014). "The underlying mechanism may be that the early administration of glargine reduces the damage to β cells and target organs that is caused by high plasma glucose levels, which activates the insulin signaling pathway and improves insulin resistance." (PMID 24944613, 2014). "Type 2 diabetes is characterized by abnormally high blood glucose levels (hyperglycemia) due to insulin resistance that may progress toward pancreatic β-cell dysfunction and a generalized loss of insulin sensitivity in the later stages of disease." (PMID 25071725, 2014). "Given our finding, we hypothesise that the mechanism causing insulin resistance starts when the subcutaneously administrated insulin is captured in the tissues." (PMID 24711924, 2014). "All aspects of the human body must be considered to better understand the mechanisms of insulin resistance and to appreciate how insulin deficiency and insulin excess may coexist in this pathologic condition." (PMID 25486190, 2014). "By the further valid target genes analysis, it is represented that the miR-182 has potentially an important role in the pathogenic process of T2D including the insulin resistance, insulin secretion, and the cell apoptosis which potentially cause tissue impairment." (PMID 25530976, 2014). "Indeed in human infants, a transition from enhanced insulin sensitivity during rapid early weight gain to insulin resistance has been observed, in association with a propensity for central fat accumulation." (PMID 24603546, 2014). "However, we identified two variants rs3758539 and rs34571439 associated with insulin levels and insulin resistance in women with previous GDM." (PMID 24665145, 2014). "Interestingly, in mammals, the membrane-bound PTP1B has been reported to have an inhibitory effect on the insulin signaling pathway, leading to insulin resistance, and has also been shown to be capable of causing an increase in blood glucose." (PMID 25137153, 2014). "However, the coexistence of hyperglycemia, insulin resistance, and other hormonal and metabolic changes in patients with Type 2 diabetes makes it difficult to understand the causative role of excess insulin signaling in the pathophysiology of hyperinsulinemia." (PMID 24795642, 2014). "One study investigated the molecular mechanisms behind skeletal muscle insulin resistance in ovariectomized rodents and found that ovariectomy led to decreased Akt signaling in response to insulin in skeletal muscle, which was associated with increased levels of phosphorylation of JNK." (PMID 25000528, 2014).
Insulin resistance (continued). "Insulin deficiency or insulin resistance may be responsible for dyslipidemia because insulin has an inhibitory action on HMG-CoA reductase, a key rate-limiting enzyme responsible for the metabolism of cholesterol-rich LDL-c particle." (PMID 25593725, 2014). "This succession of reactions is followed by posttranslational proteic modifications, which have been related to various biological processes, especially those regulating the metabolism of carbohydrates and insulin sensitivity, associated with glucotoxicity and insulin resistance (IR)." (PMID 24678419, 2014). "TNFα causes insulin resistance by directly acting on muscle insulin signaling." (PMID 24705496, 2014). "CRP is associated with insulin resistance while IL-6 may interfere with insulin signalling through induction of proteins that bind to the insulin receptor." (PMID 25548896, 2014). "Previous reports have shown that individuals may be predisposed to the development of T2D if they carry risk alleles which may predispose to impaired insulin secretion and insulin resistance." (PMID 25247988, 2014). "Furthermore, deficiencies in insulin signaling downstream of the IR have been heavily studied as a cause of insulin resistance in humans." (PMID 25259572, 2014). "Postprandial hyperglycemia causes insulin resistance by many mechanisms, including enhancing advanced glycation end products and oxidative stress, promoting production of inflammatory factors and disturbing insulin signaling pathway." (PMID 25148570, 2014). "Recent studies indicate that insulin levels vary in patients but that higher insulin levels may be associated with increased mortality, perhaps suggesting insulin resistance." (PMID 24899891, 2014). "Moreover, they also observed an association between UCP2-866G/A polymorphism and insulin resistance among 5781 middle-aged Danes and 377 young health Danes, where subjects carrying the G allele consistently had lower insulin sensitivity." (PMID 24804925, 2014). "However, there are few studies reporting the relationship between GA/A1c ratio and BMI in association with insulin secretory function, insulin resistance, and serum glucose level." (PMID 24586809, 2014). "Furthermore, when fed with a high fat diet, ATF6α null mice developed insulin resistance associated with impaired insulin secretion and lower insulin content, reinforcing the idea of a key role of ATF6α in β cells adaptation and insulin resistance." (PMID 24812634, 2014). "The hypokalaemia and hypomagnesaemia found in the present study could be a result of elevated insulin concentrations in the blood caused by hyperglycaemia and insulin resistance, as reported in critically ill humans and horses." (PMID 25274423, 2014). "Therefore, the down-regulation of SERCA is a beneficial adaptation mechanism that enables beta-cells to secrete more insulin to compensate for the loss of beta-cell mass in type I diabetes or to overcome insulin resistance in type II diabetes." (PMID 25053525, 2014). "From the other hand in the early phase of obesity level of plasma glucose can be normal but associated with hyperinsulinemia which indicates that insulin resistance is present and high insulin levels may be compensatory due to direct hypersecretion of β cells." (PMID 25030027, 2014). "However, the IRS-2 requires a higher insulin concentration for activation, the hallmark of insulin resistance." (PMID 25310961, 2014). "The previous studies also suggested that LEPR Gln223Arg polymorphism has been associated with insulin resistance capacity and an altered leptin-binding activity and the leptin can modulates insulin secretion and action via leptin receptors in pancreatic β cells." (PMID 24444121, 2014). "Besides, it was shown that depletion of PPARγ in adipose tissue causes insulin resistance, since decreased PPARγ action in mature adipocytes, leads to reduced expression of key genes required for insulin signaling in adipocytes." (PMID 25534067, 2014).
Insulin resistance (continued). "Interestingly, various hormones associated with insulin resistance and obesity including catecholamines, insulin, glucocorticoids, TNFα and IL-6 down-regulate adiponectin expression and secretion in fat cells in vitro." (PMID 24968098, 2014). "It is currently well accepted that regular physical exercise is an effective therapeutic intervention to reduce the risk of developing insulin resistance by improving glucose tolerance and insulin action in individuals predisposed to developing type 2 diabetes." (PMID 25136143, 2014). "However, even relatively short bouts of sleep deprivation (SD) have been experimentally demonstrated to reduce glucose tolerance by as much as 40%, to suppress the acute insulin response, and to cause marked insulin resistance in peripheral tissues." (PMID 24102714, 2014). "The use of oral steroidal contraceptives is associated with a reduction in insulin sensitivity and low estrogen levels, suggesting that estrogens may protect females against insulin resistance." (PMID 25646091, 2014). "HP infection does not significantly increase insulin resistance in nondiabetic individuals but in diabetic patients; in addition to higher prevalence of HP, it causes a higher degree of insulin resistance and needs higher levels of insulin for the same control similar to seropositive subjects." (PMID 25405220, 2014). "Resistance to insulin action within the CNS may be in parallel or associated with peripheral insulin resistance, but it is also possible that variable insulin resistance syndromes exist so that resistance at one tissue may be independent from that of others." (PMID 25365428, 2014). "Insulin deficiency or insulin resistance may be responsible for dyslipidemia, because insulin has an inhibitory action on HMG-coA reductase, a key rate-limiting enzyme which is responsible for the LDL particle metabolism with cholesterol-rich content." (PMID 24616741, 2014). "However, chronically elevated levels of FFAs in circulation have been postulated to cause peripheral insulin resistance and impairment of β-cell insulin secretion, a phenomenon that has been termed “lipotoxicity”." (PMID 26237395, 2014). "In addition, we found association between rs34571431 and rs3758539 with insulin concentrations and insulin resistance in GDM subjects at postpartum." (PMID 24665145, 2014). "The ongoing debate regarding the association among chronic inflammatory states; insulin resistance and obesity provide a conflicting hypothesis that chronic inflammatory state originates from obesity and drives the insulin resistant condition." (PMID 25276234, 2014). "However, reports on associations between insulin secretion or insulin resistance and 25-(OH)D have been inconsistent." (PMID 24868538, 2014). "Glucocorticoid (GC) therapies may adversely cause insulin resistance (IR) that lead to a compensatory hyperinsulinemia due to insulin hypersecretion." (PMID 25313308, 2014). "The loss of pulsatile insulin secretion alone is known to cause insulin resistance." (PMID 24741073, 2014). "Additionally, exogenous insulin administration can help to overcome the insulin resistance and insulin deficiency that occurs in CCB toxicity." (PMID 24713415, 2014). "Since eNOS deficiency was shown to reduce insulin sensitivity, this may be due to the enhanced insulin resistance in these mice." (PMID 25371905, 2014). "However, rs34571431 and rs3758539 showed associations with insulin levels and with insulin resistance in GDM subjects at postpartum." (PMID 24665145, 2014). "Lipotoxicity underlies the insulin-deficient state, especially insulin resistance." (PMID 24651118, 2014). "For example, PT transport stimulation by insulin may be involved in the pathogenesis of hypertension associated with insulin resistance." (PMID 24982885, 2014). "The insulin resistance is associated with changes in expression of key insulin signalling proteins." (PMID 24749062, 2014).